CCND1 (cyclin D1)
Diseases named in the same sentence as CCND1 in open-access papers (continued):
Sharing a sentence is not in itself a finding about the gene and the disease.
tumor (continued). "CCND1 is involved in senescence and amplification, which may be key points associated with tumor proliferation and apoptosis." (PMID 34484348, 2021). "PT2385 inhibited the expression of HIF2α-dependent genes, including VEGF-A, PAI-1, and cyclin D1 in ccRCC cell lines and tumor xenografts; and treatment of tumor-bearing mice with PT2385 caused tumor regressions, suggesting HIF2α is a pivotal oncogenic driver of human ccRCC." (PMID 34384473, 2021). "The overexpression of CDK4 and cyclin D1 in combination was also associated with advanced tumor." (PMID 34395284, 2021). "Of note, the vast majority of tumor cells were cleared from PB at timepoint V6, but with scRNA-seq, we were able to detect a single tumor cell in sample V6 and this tumor cell harbored the CCND1 E36K mutation, a mutation that associated with ibrutinib resistance." (PMID 34001881, 2021). "Additionally, another research group demonstrated an association between high cyclin D1 gene expression and high-grade tumor development, increased Ki-67 expression, and poorer survival in the ER-positive breast cancer group." (PMID 33920506, 2021). "It was therefore hypothesized that Cyclin D1 and Ki-67 will have more association with metastatic and poorly differentiated tumours." (PMID 31983161, 2020). "Indeed, a positive association between MCM7 and Cyclin D1 expression is found in mouse models and human tumor tissues." (PMID 33317149, 2020). "Dysregulated proliferation is a significant hallmark of tumor cells, and the regulatory factors include antiapoptotic proteins (e.g., Bcl-xL, and Mcl-1) and proliferation regulatory proteins (e.g., cyclin D1, Myc, and survivin)." (PMID 32957082, 2020). "The independent occurrence of these patterns, which involve the amplification of CCND1, in two different tumor samples (SA528848 and SA503541) demonstrates a mutational mechanism mediated by L1 retrotransposition, which likely contributes to the development of human cancer." (PMID 32024998, 2020). "Costaining of cancer cells with a pan-cytokeratin antibody and underexposing the immunofluorescence (IF) signal provides an effective way of delineating the cellular boundaries, revealing tumor cores with clusters of cells displaying membrane-associated cyclin D1." (PMID 32948740, 2020). "These patient tumor IHC data are in support of our in vitro findings and confirm that cyclin D1 deficiency and lower CDK4 expression is a unique feature of SCCOHT; these samples also retained the known RB/p16 profile associated with positive responses to palbociclib." (PMID 30718512, 2019). "Having CDK dependent and independent functions, cyclin D1 may cause to maturation and differentiation of tumor cells and its over expression is expected to be associated with poor prognosis as well." (PMID 31608167, 2019). "Moreover, quercetin is known to selectively affect cancer cell proliferation, reduce cyclin D1 activity, induce G1 phase arrest and cause tumor regression by activating the mitochondrial apoptotic pathway." (PMID 31337340, 2019). "However, we found that patients with high CCND1 expression had a lower risk of tumor recurrence in ccRCC compared to those with low CCND1 expression." (PMID 31183974, 2019). "Different from many other types of cancer, the decreased expression of CCND1 in ccRCC acts as a favorable prognostic factor, which could be integrated with tumor grade to generate a nomogram to predict recurrence risk for ccRCC patients." (PMID 31183974, 2019). "While such treatment successfully reduces tumor size, it may also accumulate reactive oxygen species and increase Cyclin D1 expression, which have been linked to the increase in migration and invasion." (PMID 29911682, 2018). "Treatment with piR-8041 led to increased expression of tumor suppressor RASSF1, which encodes a tumor suppressor shown to mediate cell cycle arrest at the G1/S-phase transition via inhibition of cyclin D1 accumulation and also shown to induce apoptotic cell death." (PMID 30701019, 2018).
tumor (continued). "It is reported that the overexpressed cyclin D1 has association with an increase not only in tumor progression but also in poor outcome of patients, and downregulation of cyclin D1 expression may be a potential treatment for malignant neoplasms." (PMID 29419740, 2018). "A great body of studies have disclosed that the tumorigenesis and progression of HCC are implicated with the mutation and abnormal expression and of genes, involving epidermal growth factor receptor (EGFR), cyclin D1 (CCND1), FoxQ1, c-myc, as well as mutations of some tumor-suppressor genes." (PMID 29977454, 2018). "To investigate whether a decrease in tumor size due to zingerone is associated with a low expression of cyclin D1, we examined the level of cyclin D1 via immunohistochemistry." (PMID 30235818, 2018). "The wtKLF6 is associated negatively with cyclin D1 in tumor tissues (p = 0.048)." (PMID 29854578, 2018). "In addition, we confirmed that expression levels of EGFR and Src and those of their target genes encoding c-Myc and cyclin D1 were also significantly inhibited in the tumor." (PMID 29641465, 2018). "Interestingly, Smad4cKO prostate tissue displayed normal features when stained for β-catenin, Ki67, CK8, CK14, cyclin D1, and AR, indicating that loss of both tumor suppressors is required to cause this observed phenotype." (PMID 29113300, 2017). "Since, activated STAT3 protects tumor cells from apoptosis and promote cell growth by regulating multiple genes associated with cell proliferation and anti-apoptotic proteins such as surviving cyclin D1,c-Myc, Fas, Mcl-1, Bcl-xL, and Bcl-2." (PMID 29254150, 2017). "Cyclin D1 has been found to be associated with tumor progression in numerous different tumor types." (PMID 28545522, 2017). "Tumor size, lymph node, and CCND1 amplification were associated with shorter DFS." (PMID 29140993, 2017). "Cyclin D1 protein is associated with cell cycle and tumor progression." (PMID 28545522, 2017). "Loss of parafibromin expression leads to over expression of cyclin D1 leading to tumor growth." (PMID 29354025, 2017). "Furthermore, a positive association between MCM7 and cyclin D1 expression was found in mouse model and human tumor tissues." (PMID 28182015, 2017). "Cyclin D1 is response for cell progression through G1 phase, and overexpression of Cyclin D1 enables cells with unrepaired structural or genomic damage to traverse the G1/S checkpoint, thus increasing the risk of tumor formation." (PMID 28157708, 2017). "In addition to playing a role in cell migration, cyclin D1 has been associated with tumour invasiveness and metastasis." (PMID 29066743, 2017). "These tumor-causative mutations lead to inappropriate stabilization of β-catenin, which persistently activates target genes associated with cell proliferation and transformation, such as cell cycle drivers cyclin D1 (CCND1) and c-Myc." (PMID 27556491, 2016). "Ccnd1 has been also associated with tumor invasion and metastasis in clinical studies." (PMID 27105504, 2016). "CCND1 dysregulation was associated with cellular proliferation and tumor growth of lung tumor." (PMID 27634882, 2016). "We hypothesize that the role of Ccnd1 in the cytoplasm is mainly associated with the invasive capability of tumor cells." (PMID 27105504, 2016). "HBx also inhibits expression of miR-148a, which targets hematopoietic pre-B cell leukemia transcription factor interacting protein (HPIP), and miRNA-16 family, targeting cyclin D1 (CCND1); both mi-148a and miRNA-16 family are associated with tumor growth control." (PMID 26943571, 2016).
tumor (continued). "The expression levels of CDX2, survivin, B-cell lymphoma 2 (Bcl-2), Bcl-2-associated X protein (Bax), cyclin D1, s-phase kinase-associated protein 2 (Skp2) and c-Myc in the tumor cells were analyzed by western blotting and semi-quantitative reverse transcription polymerase chain reaction." (PMID 25738600, 2015). "Previous studies have suggested that mammary transformation and tumor development are critically dependent upon the kinase activity of cyclin D1, whereby knock-in of a kinase dead allele of cyclin D1 (K112E) dramatically inhibited tumor formation within this tissue type." (PMID 25787974, 2015). "Although the mechanism underlying the direct anticancer effect of AIMs on tumor cells is not completely understood, it is known that AIMs modulate the activity of several cancer-related proteins, including cyclin D1, CDKN1A (p21), JAK1 and STAT3, HER2, and nuclear factor kappa B (NF-κB)." (PMID 26301506, 2015). "In this context, cyclin D1 is a promising tumor-associated antigen (TAA) for MCL." (PMID 25888530, 2015). "When we stratified the pooled estimates according to tumor site, there was a positive association between cyclin D1 expression and increased tumor size in tongue SCC (OR = 2.032, 95% CI = 1.200–3.441) rather than with a mixed tumor site in the oral cavity (OR = 1.431, 95% CI = 0.758–2.701)." (PMID 24675814, 2014). "It is generally recognized that Cyclin D1 is associated with tumor malignancy and poor prognosis." (PMID 24995320, 2014). "Cyclin D1 is associated with the tumor classification and may be regarded as a potential prognostic indicator." (PMID 24223635, 2013). "Overexpressed cyclin D1 in NPC increases the risk of tumor formation and local disease recurrence." (PMID 24499623, 2013). "The data suggested a possible association between the BMI1, BCL2 and Cyclin-D1 in tumor cells." (PMID 23671559, 2013). "Cyclin D1 positive tumours were associated with higher age (p = 0.001) in women." (PMID 24256736, 2013). "This allows binding and inhibition of enzymatic activities of histone acetyltransferases such as CREB-binding protein (CBP) and p300, thus silencing expression of the cyclin D1 gene which is a cell cycle regulator frequently mutated, amplified, or overexpressed in many tumor types." (PMID 23455466, 2013). "Furthermore, overexpressed cyclin D1 is associated with enhanced tumor growth and chemotherapy resistance." (PMID 23151022, 2012). "Contained within the three amplified regions are ∼20 genes, several of which have been highlighted for their functional relevance and frequent amplification in OSCCs: Cyclin D1 (CCND1) is an oncogene previously implicated in several cancers and is 13-fold up-regulated in the tumor." (PMID 20174472, 2010). "As FHL2 plays an important role in cell proliferation, it is possible that high level of cyclin D1 may counteract FHL2 deficiency in the stimulation of tumor cell growth in ApcΔ14/+FHL2−/− mice." (PMID 20442768, 2010). "Furthermore, it has been reported that antisense to cyclin D1 inhibited tumor-associated neovascularization." (PMID 20843378, 2010). "Moreover, CCND1 expression is considered an early event in malignancy and its loss inhibits tumor formation in a Ptch1+/- mouse model." (PMID 18826648, 2008). "Cyclin D1 overexpression has been found implicated in several types of human neoplasias." (PMID 18651966, 2008). "Investigations to challenge the impact of cyclin D1 expression revealed that cyclin D1-positive tumours associated with significantly lower preoperative PSA values, indicating that cyclin D1 status may influence tumour marker expression." (PMID 17375037, 2007).
tumor (continued). "Furthermore, the proliferative index tended to be lower in the cytoplasmic cyclin D1 tumours than in the cyclin D1-deficient tumours." (PMID 17375037, 2007). "Intragenic somatic mutations of cyclin D1 are rare, but a polymorphism of cyclin D1 that occurs in a splice donor site has been epidemiologically linked to increased cancer risk or poor prognosis in a number of tumor types." (PMID 16863592, 2006). "Cyclin D1 is a key regulator of cell cycle progression, and a target of β-catenin, a protein whose abnormal accumulation in the nucleus is strongly linked to the development of multiple tumor types, including those of the colon." (PMID 15644144, 2005). "Interestingly, low protein contents of cyclin D1 and p27 were associated with high nuclear grade, large tumour size, and poor prognosis for patients with conventional tumours." (PMID 12778072, 2003). "Furthermore, they discovered an enrichment of CCND1 mutations within precancerous lesions and demonstrated that cancer-associated fibroblasts possess stem-cell-promoting properties, underscoring their role in tumor progression." (PMID 40365340, 2025). "Similarly, the overexpression of miRNA-21 and cyclin D1 is a hallmark of tumor initiation." (PMID 40096320, 2025). "Moreover, c-myc and cyclin D1 are typical tumor-associated genes." (PMID 40308769, 2025). "Therefore, the observed decrease in tumor size following LC‐1/sulindac combination or high‐dose sulindac treatments may be attributed to the prevention of cyclin D1 production, causing significant chemosensitivity." (PMID 40051490, 2025). "Cyclin D1 is a necessary protein for the cell cycle to continue through the G1 phase, where its over-expression has been linked to early cancer onset and tumor development and could promote oncogenesis by boosting anchorage-independent growth and angiogenesis via VEGF production." (PMID 37845669, 2023). "Moreover, we uncovered a direct relation between the cyclin D1 expression and the stiffness of the 3D cell culture milieu, suggesting the potential causal involvement of the cyclin D1 as a bio-marker for sensitivity of the tumour cells to their matrix stiffness." (PMID 38046276, 2023). "Given the evidence of a possible VSV-associated enhanced T cell reactivity against SIINFEKL, it is difficult to interpret the significance of the responses to hTERT or Cyclin D1 as they might reflect epitope spreading against possible tumor associated antigens." (PMID 38022659, 2023). "The literatures suggest that reducing the expression of Ccnd1 through antisense technology causes a concomitant decline in Ccnd1-dependent kinase activity and results in inhibition of tumor growth, abolition of tumorigenicity, or, in some instances, tumor cell death." (PMID 35462890, 2022). "In addition, insulin has also been shown to influence glucose metabolism through the regulation of cyclin D1-cyclin dependent kinase (Cdk) 4 activity, rendering hyperinsulinemia-associated tumor growth susceptible to CDK4 inhibitors in the context of liver cancer." (PMID 33604295, 2020). "Thus, the strong Cyclin D1 expression observed in the VHL tumor may be a direct result of the loss of pVHL-dependent transcriptional repression." (PMID 31673890, 2020). "Interestingly, we also observed the crosstalk between FOXO3a and miR-30a, and FOXO3a has already been shown to have an important role as tumor suppressor, through transcriptionally regulating cell cycle- and apoptosis-associated genes such as p27, cyclin D1, and TRAIL54–58." (PMID 30770779, 2019). "Finally, our study reveals a novel paradigm whereby a critically low level of an oncogene such as cyclin D1, caused by loss of a driver tumor suppressor, may also be a cancer vulnerability that can be targeted therapeutically." (PMID 30718512, 2019).
tumor (continued). "In addition, cyclin D1 expression was directly associated with tumor recurrence (p = 0.04)." (PMID 28107179, 2017). "Indeed, the incidence of cyclin D1 overexpression was significantly higher in BRAF-mutated (58%) than BRAF wt tumours (14% P=0.001), and patients with BRAF mutations and cyclin D1 overexpression had significantly decreased PFS (P=0.03) and OS (P=0.01) compared with patients with BRAF wt tumours." (PMID 20485284, 2010). "Despite the clear association of tumor budding with migration and invasion, paradoxically, tumor buds seem to undergo low rates of proliferation as evidenced by reduced expression of proliferation marker Ki67 and concomitant increased expression of cell-cycle arrest mediators cyclin D1 and p16." (PMID 21317460, 2010). "In addition, increase cyclin D1 expression in tumor samples suggested that partial loss of tuberin is sufficient to upregulate cyclin D1 that may enhance cell proliferation in tumor cells tissue." (PMID 19265534, 2009). "Furthermore, the tumor material allowed us to study prognostic features, relations with different clinicopathological parameters, and associations with CCND1 amplification, in different subgroups defined by the expression of the 11q13 and distal 11q gene products." (PMID 18823530, 2008). "Intriguingly, the selective GR modulators (SGRMs) C134 and C335 were shown to reduce MCF-7 ESR1 mutant primary tumor growth by decreasing the expression of CCND1." (PMID 41261233, 2026). "AMBP overexpression in CCA cells activated WNT molecules (β-catenin, c-Myc, and Cyclin D1), enhancing tumor progression." (PMID 41824874, 2026). "GPC-3 promotes tumor growth by enhancing canonical Wnt/β-catenin signalling, leading to increased expression of oncogenes such as c-Myc and Cyclin D1." (PMID 41511652, 2026). "For instance, epidermal growth factor receptor (EGFR) and cyclin D1 can be detected through mRNA analysis and can be correlated with tumor progression or a poor prognosis." (PMID 40096320, 2025). "The β-catenin bound TCF/LEF transcription factors result in the upregulation of downstream genes c-myc, cyclin D1, mmp7, mmp9, and MDR1 which normally function in early embryogenesis, but have been linked to neoplasm formation." (PMID 40001961, 2025). "PHB2 regulates cell cycle progression by modulating cyclin expression: its upregulation enhances Cyclin D1 and Cyclin E (G1/S transition) and Cyclin A and Cyclin B (S/G2 progression), driving tumor growth." (PMID 40076502, 2025). "In our study, multivariate analysis showed that PD-L1 and cyclin D1 are factors that increase the odds of tumor invasiveness (OR (95% CI) 2.35 (0.56–9.90) and 1.93 (0.42–8.84), respectively)." (PMID 40869149, 2025). "Downstream of β-catenin, target genes such as TCF1, Cyclin D1, Axin2, Lgr5, and c-Myc promote cell cycle progression in both tumor cells and SSCs." (PMID 40638605, 2025). "Expression of cyclin D1 increased as the tumor grade increased from 9.7% in well-differentiated and 66.6% in non-keratinizing ones." (PMID 41541922, 2025). "In our study, upregulation of miR-20b enhanced γ-H2AX levels and reduced CCND1 expression following radiotherapy, ultimately suppressing tumor growth." (PMID 41395621, 2025). "Slower tumour growth rate was accompanied by a reduced expression of Ki67 and cyclin D1 and a lower accumulation of pSTAT3." (PMID 40673604, 2025). "The average Ct value for CCND1 expression was lower in tumor tissues (4.42) compared to peritumoral tissues (5.05), corresponding to a higher gene expression in the tumor samples." (PMID 40344393, 2025). "As a component of the cell cycle mechanism, changes in the expression of cyclin D1 affect the cell cycle progression, thereby altering the killing effect of antitumor drugs on tumor cells." (PMID 39712859, 2025). "The IL‐11/IL‐11RA signalling pathway and tumour proliferation were significantly down‐regulated as assessed by IHC staining of pSTAT3, and cyclin D1 and Ki67, respectively." (PMID 40673604, 2025).